IRF3 (interferon regulatory factor 3)
Diseases named in the same sentence as IRF3 in open-access papers (continued):
Sharing a sentence is not in itself a finding about the gene and the disease.
viral infection (continued). "These events include the transcription of type I interferon, chemokines and cytokines in a manner that depends on the presence IRF-3, a transcription factor that has a central role in the response of the immune system to viral infection." (PMID 23251783, 2012). "Given the importance of IRF3 and type I IFN in protection against virus infection, it is likely that all viruses encode mechanisms to disable these proteins." (PMID 22363706, 2012). "Very recently, it has been described that MAVS forms functional prion-like aggregates after viral infection and that these aggregates are required for the activation of IRF3 in the cytoplasm." (PMID 22626058, 2012). "The gene IRF3 regulates the expression of Type I IFNs (cytokines with antiviral activity), and thus controlls viral infection and virus replication." (PMID 23206407, 2012). "Upon activation in response to TLR agonists and viral infection, IKKε phosphorylates IRF3 and IRF7 and triggers IRF3/IRF7 nuclear translocation, which results in the up-regulation of type I IFN expressions." (PMID 22783275, 2012). "TBK-1 was previously identified as a kinase that phosphorylates the carboxyl terminus of the related transcription factor, IRF3, in response to viral infection." (PMID 22412986, 2012). "The induction of type I IFNs is the earliest cellular immune response initiated to combat viral infections and is coordinated by the activation of transcription factors such as interferon regulatory factor (IRF)-3, IRF7, and NFκB downstream of PRR activation." (PMID 21436888, 2011). "Viral infection or other stimulation induces phosphorylation of IRF3 and the formation of IRF3 homodimers, leading to the activation of innate antiviral responses." (PMID 22039483, 2011). "Upon viral infection, IRF3 is hyperphosphorylated on multiple serine and threonine residues located at the C-terminus." (PMID 21347389, 2011). "A related transcription factor of the IRF family, IRF7, also plays an important role in anti-viral responses and can be activated in a similar manner to IRF3 during viral infection." (PMID 21931555, 2011). "Taken together with previous observations, these data strongly suggest that the degradation of phosphorylated (activated) IRF3 protein is a primary mechanism for the transcriptional turn-off of the IFNβ gene during acute virus infections." (PMID 21677781, 2011). "It has been previously demonstrated that the two non-canonical IκB kinase homologs, namely IκB kinase-ε (IKK-ε or IKKi) and TANK-binding kinase-1 (TBK1), are involved in the C-terminal phosphorylation of IRF3 upon dsRNA stimulation or viral infection." (PMID 21347389, 2011). "Activation of PKR signaling during virus infections is known to result in IRF3 phosphorylation and concomitant IFNβ production." (PMID 21698289, 2011). "We report that the transcription factor IRF3 plays a central role in the negative regulation of interferon-β (IFNβ) expression during both acute and persistent (chronic) virus infections." (PMID 21677781, 2011). "Virus infection leads to the activation of at least three families of transcriptional factors: NF-κB, IRF-3 and AP-1." (PMID 19592477, 2011). "We note that virus infection also induced some degradation of IRF3 in Namalwa cells, but, the level of the phosphorylated IRF3 remained high as late as 24 hrs post-infection." (PMID 21677781, 2011). "Because IRF3 plays a major role in the type I IFN response to viral infection, many viruses have developed different strategies to subvert the host immune response by targeting this pathway." (PMID 21347389, 2011). "Western blot analyses reveal that the level of IRF3 correlates with IFNβ gene expression during acute virus infection." (PMID 21677781, 2011). "Activation of IRF-3 or IRF-7 is a critical step during virus infection, promoting the most potent type I IFN production." (PMID 21936899, 2011).
viral infection (continued). "IFN-mediated anti-viral effects are carried out using different mechanisms that are dependent on the type of viral infection, but these anti-viral effects are all dependent on IRF-3 activation." (PMID 21936899, 2011). "This activation of IRF3 results in the trans-activation of genes responsible for combating viral infection including interferon beta." (PMID 22174679, 2011). "IRF3 is ubiquitously expressed in the cytoplasm and is activated in response to viral infection, triggering IFN-β and other early ISGs expression, thus initiating the antiviral response." (PMID 21079688, 2010). "Altogether, these data demonstrate that NOX2 and ROS are essential for the efficient activation of IRF-3 during virus infection." (PMID 20532218, 2010). "In particular, IRF-3 is ubiquitously expressed and accumulates in the cytosol to enable a rapid response to viral infection and up-regulate the type 1 IRF." (PMID 21134281, 2010). "IRF3 was originally described as a transcription factor controlling interferon responses to viral infection." (PMID 20886096, 2010). "We and others have previously demonstrated that IKK-related kinases, IKKε and TBK1, are part of the kinase activity that is essential for IRF-3 phosphorylation and subsequent activation of IRF-3 in the context of virus infection." (PMID 20532218, 2010). "In the cellular response to virus infection, IRF3 and IRF7 play a predominant role in the transcriptional induction of the type I IFN (IFN-I) family, comprised of a single IFNβ gene and a cluster of IFNα genes." (PMID 21994600, 2010). "Viral infection leads to activation of Interferon Regulatory Factor 3 (IRF3), IRF7 (if present in the infected cell) as well as nuclear factor kappa B (NFκB)." (PMID 27713280, 2010). "For example, although IRF3-null mice were significantly more vulnerable to viral infection than WT mice, fibroblasts harvested from IRF3-null mice displayed normal antiviral responses." (PMID 20454685, 2010). "Toll-like receptors (TLR) 3 and 4 are pathogen associated molecular pattern receptors that can specifically lead to IRF-3 activation and trigger the transcription of genes involved in the defense against viral infection." (PMID 21994610, 2010). "Upon viral infection, IRF-3 and IRF-7 are phosphorylated at their carboxy-termini (C-terminus), which leads to dimerization, nuclear translocation, and association with other trans-activator proteins." (PMID 21994610, 2010). "IRF3 dimer formation was detected only in IKKγ-WT- expressing cells in response to either type of viral infection." (PMID 19956647, 2009). "Together we conclude that the relative IKKγ-WT∶IKKγΔ ratio, independent of changes in total IKKγ abundance, controls cellular IRF3-IFN responsiveness to ssRNA virus infection." (PMID 19956647, 2009). "Both IRF3 and NF-κB signaling play important, yet distinct, roles in anti-viral and inflammatory signaling in response to ssRNA viral infection." (PMID 19956647, 2009). "In summary, our experiments suggest that IRF-3 signals the host to control viral infections and/or initiate IFN responses by distinct mechanisms in different cell types." (PMID 17676997, 2007). "The underlying mechanism involves DYRK4 acting as a scaffold protein to recruit TRIM71 and LUBAC to IRF3, increasing IRF3 linear ubiquitination, maintaining IRF3 stability and activation during viral infection, and promoting the IRF3-mediated antiviral response." (PMID 39702801, 2025). "In addition to NF-κB, IRF3 activation is an early response to viruses in human cells and is involved in the induction of several immune genes in human DCs in response to a viral infection, which led us to investigated its activation in response to HZ and LPS." (PMID 40717771, 2025). "Moreover, our findings align with studies showing that IRF3 can still be induced after viral infection even when IRF1 is knocked down, suggesting their independent activation." (PMID 40643511, 2025).
viral infection (continued). "They confirmed the key role of IRF3 in the host's resistance to viral infection." (PMID 40245000, 2025). "We further explored these phenomena in additional human and mouse systems by conducting remarkably sensitive/specific IRF3- and H3K27ac-ChIP-seq experiments prior to and upon virus-infection (SVI, 0 and 6 h), in human lung cells (A549), and mouse fibroblasts (NIH/3T3)." (PMID 40131776, 2025). "Although IRF7 may not be mediating the IFNβ induced expression of EphB2, the ablation of IRF7 alone does induce transcription of IRF3, the long-non-coding RNA HEAL and NF-kB, three factors implicated in viral infection and inflammation." (PMID 40588746, 2025). "Additionally, NSUN2 has been shown to be a negative regulator of type I IFN responses during viral infections by degrading IRF3 mRNA; its knockout or knockdown enhances IRF3 mRNA and protein levels, thereby amplifying IFN responses." (PMID 41059804, 2025). "TBK1 is known to activate STAT1 through IRF3/7 in response to viral infections." (PMID 39415484, 2025). "IRF3 has been shown to undergo autophagic degradation in response to viral infection." (PMID 39702801, 2025). "More importantly, the double mutant IRF3 degraded rapidly upon viral infection (Fig. EV4K)." (PMID 39702801, 2025). "Although the DUB OTUD1 has been shown to remove K63-linked polyubiquitination in autoimmune disease models, its involvement in early innate immune responses by reducing IRF3 K63 ubiquitination is minimal, primarily due to its upregulation during viral infection." (PMID 39761299, 2025). "In DFO-treated PMs, FPN1 deficiency had no inhibitory effect on viral infection-induced cytokine expression or the phosphorylation of IRF3 and TBK1." (PMID 40595467, 2025). "Although the pro-apoptotic activity of IRF3 was beneficial in fighting viral infections, it could also lead to liver cell death and exacerbate detrimental immune responses in liver disease." (PMID 38999981, 2024). "Consistently, 3-HB can promote virus-induced IRF3 phosphorylation during virus infection." (PMID 38809975, 2024). "Upon viral infection, IRF3 becomes activated by phosphorylation of its specific serine residues." (PMID 39362857, 2024). "To further determine whether the antiviral activity of PBLD is dependent on IRF3, we transfected PBLD into IRF3-overexpressed or IRF3-knockout cells upon virus infection." (PMID 39362857, 2024). "This drove us to further evaluate effect of ATG7 on the activation of IRF3 upon viral infection." (PMID 38227600, 2024). "In response to VSV infection, IRF3 prolyl hydroxylation initially increased (2 h) and then decreased (4 h), suggesting a transient physiological role for IRF3 prolyl hydroxylation in response to viral infection." (PMID 38670937, 2024). "In addition, the virus stops the host cell from identifying and reacting to the viral infection by suppressing IRF3 and IRF7 activation." (PMID 38355695, 2024). "NDP52 mediates the selective degradation of IRF3 upon viral infection." (PMID 38660307, 2024). "Thus, IRF3-dependent gene expression provides the host cell with the ability to immediately deploy some of the best studied ISGs to counter the commencing viral infection (21, –, 24)." (PMID 37289084, 2023). "It eventually activates the IKK complex, which further activates IRF3 and NF-κB-mediated signaling pathways and induces the expression of type I interferons and pro-inflammatory factors, which have a very important innate immune effect during viral infection." (PMID 38005850, 2023). "Additional studies will be required to address the interplay and effect of the herpesviral immune modulators in the course of type I IFN signaling during viral infection, as well as the potential involvement and regulation of IRF3 and NF-κB in herpesviral gene expression." (PMID 37289084, 2023). "Phosphorylation and dimerization are two hallmarks of IRF3 activation after viral infection." (PMID 37871014, 2023).
viral infection (continued). "Consequently, our results indicate circMORC3 and host gene MORC3 can synergistically inhibit TRIF and IRF3 in the TLR signaling pathway at different stages of viral infection, promoting viral immune escape." (PMID 38150467, 2023). "In addition, viral infection can stimulate the induction of the β-catenin-IRF3-CBP/p300 complex, which also contributes to IFN-β production." (PMID 37022262, 2023). "In addition to its transcriptional activity, IRF3 has been shown to counter viral infection by two additional mechanisms." (PMID 37733807, 2023). "Nevertheless, we found that IRF3 was efficiently phosphorylated during viral infection." (PMID 37197656, 2023). "In addition to regulating IRF3 activity, IKKi is also critical for NF-κB activation, which mediates p65 (Ser536) phosphorylation in response to proinflammatory signals and viral infection." (PMID 37022262, 2023). "Upon viral infection, cytoplasmic IRF3 is phosphorylated and forms dimers." (PMID 37410776, 2023). "Upon viral infection, IRF3 undergoes serial processes of phosphorylation." (PMID 37871014, 2023). "The phosphorylation of IRF3 by TBK1/IKKε is crucial to induce IFN-I in response to virus infection." (PMID 37673879, 2023). "The transcriptional activities of IRF3 in both Optn-KO and WT MEFs were greater by viral infection." (PMID 37352136, 2023). "Additionally, MAVS aggregation, IRF3 dimerization, and phosphorylation were enhanced in Wdr77CKO PEMs upon virus infection." (PMID 37563140, 2023). "The RIKA function of IRF3 may be explored further in other inflammatory diseases beyond viral infection." (PMID 37515265, 2023). "IRF1 has been reported to interact with IRF3 to enhance its activation during viral infection." (PMID 36307867, 2022). "Additionally, inhibition of mitochondrial fusion by knockdown of MFN-2 resulted in decreased NF-κB and IRF3 activation during viral infection." (PMID 36552877, 2022). "IRF3 plays a critical role in the IFN-β response to viral infection." (PMID 35180274, 2022). "Synthesized 2′,3′-cGAMP interacts with ER-resident STING and triggers downstream signaling of type I IFNs through TBK1 and IKK, inducing the activation of IRF3 and releasing cytokines, including type I IFNs, the first line of defense against viral infections (50, –, 55)." (PMID 35861515, 2022). "Overexpression of SNX5 can inhibit the virus-induced activation of nuclear factor kB (NF-kB) and Type-I interferons (IFN) regulatory factor 3 (IRF3), which may lead to a decrease in the cell’s ability to fight viral infection." (PMID 35898490, 2022). "Also, the IRF3/IRF7 heterodimer is commonly known to be involved in viral infection, inflammatory diseases." (PMID 34996392, 2022). "The induction of IFN production by viral infection relies on the activation of IRF3." (PMID 36307867, 2022). "However, another study found TRIM21 stabilizes IRF3 expression resulting in an increase in resistance to virus infection; in this case, against Sendai virus." (PMID 35336995, 2022). "Although RT-qPCR analysis and luciferase reporter assays indicated that NSP5 can suppress the induction of type I and type III IFNs, its effect on IRF3 phosphorylation during viral infection is unknown." (PMID 35075101, 2022). "IRF3 activation is essential for the production of type I IFNs during virus infection." (PMID 36329446, 2022). "Viral infection can also reduce PTEN expression to inhibit nuclear translocation of IRF-3." (PMID 36189363, 2022). "Upon virus infection, IRF-3 is activated to promote antiviral responses." (PMID 35273248, 2022). "Viral infection triggered IRF3 phosphorylation in both circRIG-I-expressing and control cells." (PMID 36402769, 2022). "Importantly, IFNβ expression can be induced through different IRF3-mediated signaling pathways, which can be activated by distinct nucleic-acid-sensing receptors and viral infections." (PMID 36173315, 2022).
viral infection (continued). "We hypothesized that upon genotoxic insult, IRF1 might be a downstream target of the RLR/IRF3 pathway, as reported for virus infection, and thereby link RLR activity to the DNA damage response." (PMID 35436994, 2022). "Rbck1 mediates IRF3 ubiquitination for proteasomal degradation upon viral infection." (PMID 35280983, 2022). "Viral infection induces the E3 ligase AMFR/gp78 to constitutively interact with STING and mediate the K27-linked ubiquitination of STING, which is critical for the STING-mediated recruitment of TBK1 and IRF3 following DNA virus infection." (PMID 35992663, 2022). "In addition, we found that DDX3 promotes IRF-3-mediated IFNB promoter activation and augments IFN-β production in response to viral infection through its interaction with IRF-3." (PMID 35273248, 2022). "It is required for the activation of IFN regulatory factor 3 (IRF3) after viral infection." (PMID 35180274, 2022). "Upon viral infection, IRF3 in the cytoplasm of the infected cells is phosphorylated by the kinases TBK1 and IKKε, and undergoes a conformational change and homo-dimerization, which permits its translocation to the nucleus where it binds the ISRE of target genes." (PMID 36082118, 2022). "Mechanistically, upon viral infection, IRF3 ISGylation impairs the interaction of IRF3 with the peptidyl-prolyl cis-trans isomerase NIMA-interacting 1 (PIN1) and antagonizes the ubiquitination and degradation of IRF3, which results in persistent IRF3 activation and antiviral responses." (PMID 36319753, 2022). "Furthermore, immunofluorescence assays showed that TOB1 interacted with IRF3 in the cytoplasm of resting mouse embryonic fibroblasts (MEFs), and viral infection further enhanced the interaction and promoted TOB1 and IRF3 translocation to the nucleus." (PMID 36085336, 2022). "In conclusion, this study identified DExD-Box RNA helicase DDX50 as a crucial component facilitating DDX1-independent IRF3 activation following stimulation with dsRNA or viral infection and further established a pivotal role for DDX50 as a viral restriction factor for RNA and DNA viruses." (PMID 35215908, 2022). "However, the acetylation of TBK1 at Lys241 during the early stage of viral infection enhanced the recruitment of IRF3 to TBK1." (PMID 32772249, 2021). "IRF3 stability was examined using JMJD6-deficient and JMJD6-rescued cells upon virus infection." (PMID 33684176, 2021). "It recognizes dsRNA associated with a viral infection, and induces the activation of IRF3, unlike all other Toll-like receptors which activate NF-κB." (PMID 34970593, 2021). "IRF3 is a key mediator of type I IFN response triggered by viral infections." (PMID 33372854, 2021). "Therefore, while we have shown the activation of IRF3-driven apoptosis in virus infections benefits the host, the role of IRF3 in liver disease still remains somewhat unclear." (PMID 33805458, 2021). "Upon viral infection, RIG-I detects viral RNA and catalyzes the self-association of MAVS on the mitochondrial membrane and subsequent conversion into very large prion-like aggregates that potently activate IRF3." (PMID 34578357, 2021). "Therefore, we also tested to see if NSs block the nuclear translocation of IRF3 in response to viral infection." (PMID 33397830, 2021). "Based on these findings, we hypothesized that IFN-γ-mediated signals are induced by IRF3, which could generate cytokines that facilitate viral infection and IFNs that inhibit viral infections." (PMID 33479394, 2021). "In addition, the innate immune system suppresses expression of the TGF-beta receptor and the SMAD pathway via IRF3 during virus infection." (PMID 34572043, 2021). "IRF3 activation is well known to form phosphorylation-dependent dimerization upon viral infection." (PMID 33684176, 2021).